RPRML (reprimo like)
Synonyms: MGC43894
Tractability: Antibody: UniProt predicts a signal peptide or a membrane-spanning region.
Gene: Protein-coding gene on chromosome 17 (46,978,156 to 46,979,253, reverse strand). Ensembl gene ENSG00000179673.
Subcellular location: Membrane
Gene Ontology:
Cellular component: membrane
Genetic constraint (gnomAD): Loss-of-function variants: 4 observed, 4.05 expected, observed/expected ratio (o/e) 0.99, 90% interval 0.47 to 1.83. That is too few expected variants to judge how well the gene tolerates losing a copy. Missense variants: 181 observed, 151.98 expected, observed/expected ratio (o/e) 1.19, 90% interval 1.05 to 1.35. Synonymous variants: 79 observed, 74.64 expected, observed/expected ratio (o/e) 1.06, 90% interval 0.88 to 1.28.
Homologues: Orthologues: chimpanzee RPRML (99% identical), macaque RPRML (99% identical), guinea pig RPRML (92% identical), mouse Rprml (90% identical), rat Rprml (90% identical), pig RPRML (89% identical), tropical clawed frog rprml (62% identical), zebrafish rprml (56% identical). Paralogues in human: RPRM (50% identical).
Diseases named in the same sentence as RPRML in open-access papers:
RPRML is named in the same sentence as 5 diseases in open-access papers, as found by Europe PMC text mining. Sharing a sentence is not in itself a finding about the gene and the disease. The quoted sentences say what the papers report.
gastric cancer (2 papers, 2020 to 2021). A primary or metastatic malignant neoplasm involving the stomach. "Downregulation of RPRML protein expression was associated with poor overall survival in advanced gastric cancer." (PMID 33322837, 2020). "Reprimo-like (RPRML) is a member of the reprimo gene family that is a group of poorly understood single-exon intronless genes, and whose loss of expression is related to increased cell proliferation and growth in gastric cancer." (PMID 34830815, 2021). "Here, we evaluated the role of RPRML and whether its regulation by DNA methylation is a potential non-invasive biomarker of gastric cancer." (PMID 33322837, 2020).
cancer (2 papers, 2018 to 2020). A tumor composed of atypical neoplastic, often pleomorphic cells that invade other tissues. "The role of RPRML in cancer biology was investigated in vitro, through RPRML ectopic overexpression." (PMID 33322837, 2020). "In addition, in vitro gain/loss of function experiments focused on evaluation of tumorigenic or tumor suppressive effects may provide insights on the role of RPRML in cancer." (PMID 29941787, 2018). "Our results suggest that RPRML is a TSG, downregulated by DNA methylation in GC, and that circulating methylated RPRML DNA can distinguish patients with GC from cancer-free controls." (PMID 33322837, 2020).
tumor (1 paper, 2020). "The in vitro overexpression results and the poor patient survival associated with lower RPRML levels suggest that RPRML plays a tumor-suppressive role in the stomach." (PMID 33322837, 2020). "Taken together, these results suggest that RPRML reduces cell proliferation, supporting its role as a tumor suppressor in GC." (PMID 33322837, 2020). "Due to the homology with the founding member of the RPRM family, we evaluated if RPRML also possessed tumor suppressor properties." (PMID 33322837, 2020). "Correspondingly, analysis of RPRML expression in NTAM and tumor tissues showed consistent downregulation in clinical samples and was associated with worse prognosis in advanced stages of GC." (PMID 33322837, 2020).
RPRML also shares sentences with these, for which no sentence is quoted: acute myeloid leukemia (1 paper); adenocarcinoma (1).